PTH (parathyroid hormone)
Diseases named in the same sentence as PTH in open-access papers (continued):
Sharing a sentence is not in itself a finding about the gene and the disease.
Hypocalcemia (continued). "In uni-variate analyses, reduced kidney function associated not significantly with higher prevalence of high serum PTH, low serum 1,25(OH)2D and hypocalcemia among men, and with higher prevalence of hyperphosphatemia, high serum PTH, and low serum 1,25(OH)2D among women." (PMID 33371520, 2020). "However, PTX can induce hypocalcaemia and adynamic bone disease, and currently, there is no appropriate pharmacotherapy for low levels of PTH following surgical PTX." (PMID 33180218, 2020). "Interestingly, one study showed that postoperative PTH level, rather than preoperative 25(OH)D status, was a predictor of postoperative hypocalcemia." (PMID 32774362, 2020). "In contrast to this hypothesis, our group has later demonstrated that blocking the Na+/K+-ATPase by ouabain did not affect the PTH secretory response to hypocalcemia." (PMID 33233840, 2020). "Additionally, lactate and low extracellular pH have been reported to induce PTH secretion, as observed in animal and human studies, though no hypocalcemia occurs." (PMID 32751307, 2020). "In previous studies, we demonstrated that PTH, calcitriol and calcitonin are not required for the minute-to-minute recovery from acute hypocalcemia but the hormones are setting the set point for upregulation of calcium levels and hereby having an additional impact on mineral homeostasis." (PMID 33233840, 2020). "The mechanism of hypocalcemia is unknown and there was no data on vitamin D or intact parathyroid hormone (PTH) levels." (PMID 33489613, 2020). "However, during acute hypocalcemia, where increased PTH levels are necessary to reverse hypocalcemia, no inhibitory effect of FGF23 on PTH secretion was observed." (PMID 30927339, 2019). "Laboratory testing should confirm a low albumin-corrected total serum calcium level or a low ionized calcium levels and low PTH on at least two occasions (emergent care for hypocalcemia should not be delayed and does not require two test results for confirmation of hypocalcemia)." (PMID 30540559, 2019). "Asymptomatic mild hypocalcemia without elevated PTH, which is considered hypoparathyroidism, may be more common but under-recognized." (PMID 29726397, 2018). "Thus, in chronic hypocalcemia there is a marked increase in calcitriol, which has no suppressive effect on PTH levels; they are significantly increased as well." (PMID 29063159, 2018). "However, in subjects with severe HPT, there is complete lack of PTH release to counter reduced gut Ca absorption, resulting in hypocalcaemia." (PMID 28993435, 2017). "Even though decreased serum calcium is connected to disturbed vitamin D metabolism, hypocalcemia may not be specific only to nephrectomy, since hypocalcemia and secondary increase in PTH were observed after different abdominal surgeries." (PMID 28130714, 2017). "Llach and colleagues examined responses to endogenous PTH by infusing the chelating agent ethylenediaminetetraacetic acid (EDTA); in comparison to control subjects, patients with mild CKD responded to EDTA with more severe hypocalcemia, much higher [PTH], and a more delayed recovery of [Ca]s." (PMID 28445401, 2017). "Among those patients with biochemical hypoparathyroidism, three had typical symptoms of hypocalcemia (7 %), but were normocalcemic under daily substitution of calcium and vitamin D. Three patients had a recurrent HPT (7 %) according to the KDOQI-recommended PTH levels." (PMID 26467771, 2015). "However, for the kidney transplant patients with severe hypocalcemia and low PTH, treatment with teriparatide showed good results without side effects." (PMID 26649301, 2015). "High PTH levels with hypocalcemia but also hypophosphatemia ruled out hypoparathyroidism." (PMID 26640724, 2015). "All patients who exhibited a PTH level of less than 9 pg/mL 1 hour after surgery developed symptomatic and biochemical hypocalcemia requiring treatment with calcium and vitamin D. None of the patients with PTH ≥ 9 developed hypocalcemia." (PMID 24476535, 2014).
Hypocalcemia (continued). "Most of them had hyperphosphatemia without hypocalcemia and the highest PTH." (PMID 25123022, 2014). "In other words, PTH-SC had similar accuracy in predicting postthyroidectomy hypocalcemia regardless of whether the preoperative 25-OHD was <15 or ≥15 ng/mL." (PMID 22968355, 2013). "However, the group with PTH-SC ≤1 pmol/L would need closer monitoring because even though 5/19 or 26.3 % never developed clinically relevant hypocalcemia, the other 14 required some oral calcium and/or calcitriol supplements to maintain normocalcemia." (PMID 22399155, 2012). "It was suggested that intraoperative or early postoperative parathyroid hormone assay might be a sensitive tool to confirm postoperative normocalcaemia and identify patients atrisk of developing postoperative hypocalcaemia." (PMID 20798772, 2010). "Differentiating between transient and permanent hypocalcemia is critical, especially after a parathyroidectomy when hypocalcemia may result from bone hunger, rather than insufficiency of PTH." (PMID 21197072, 2010). "The finding of elevated PTH levels in the context of normocalcemia suggests that hypocalcemia may not be the only factor leading to hyperparathyroidism in PHP." (PMID 21274302, 2009). "Additionally, without magnesium supplementation, the PTH response may have been blunted due to large declines in magnesium, possibly leading to worsened hypocalcemia." (PMID 40663633, 2026). "Therefore, in patients without renal abnormalities after TT, intact PTH may not affect the accuracy of prediction of postoperative hypocalcemia." (PMID 40786097, 2025). "As a result, hypocalcemia is established, 1,25-dihydroxyvitamin D is decreased because PTH can't stimulate 1-a hydroxylase, phosphate levels rise because of the lack of phosphaturic action of PTH, and the fraction of filtered calcium at the glomerulus is inappropriately increased." (PMID 40177730, 2025). "However, regular monitoring of serum calcium and PTH levels is essential to ensure safety, especially in patients with advanced CKD particularly hemodialysis patients, where the risk of hypocalcemia is higher especially if patients had not received prior vitamin D and calcium supplements." (PMID 40708576, 2025). "However, many more patients had transient hypocalcaemia; given the similarity of results for both outcomes (transient hypocalcaemia and long-term PoSH), it would be reasonable to conclude that the drop in PTH is unlikely to be a significantly improved predictor of PoSH." (PMID 38478048, 2024). "The results demonstrated that post-thyroidectomy PTH levels accurately predict hypocalcemia but lack 100% accuracy, which may be one reason why there is still no standardized method to predict postoperative hypocalcemia." (PMID 38030913, 2023). "However, CaSR is not activated in hypocalcemia, so PTH release is stimulated." (PMID 36651710, 2023). "When examining the baseline characteristics of hypocalcemia patients who discontinued and did not discontinue within four months following hypocalcemia events, characteristics were relatively similar except baseline PTH at time of cinacalcet initiation was lower among those who discontinued." (PMID 31848883, 2020). "Thus, PTH levels in cord blood could be lower than the normal adult range as long as no hypocalcemia happened, in the condition of suppression by active placental calcium transport." (PMID 33330264, 2020). "In addition, hypocalcemia leads to increased parathyroid hormone (PTH) levels; although we did not evaluate PTH in this study, PTH changes could be an indicator of the physiological relevance of the reduced calcium levels." (PMID 27247960, 2016). "In addition, perturbations of the plasma ionized calcium concentration in vivo by intravenous infusions of calcium salts to induce hypercalcemia or Ca2+ chelators such as citrate or EGTA to induce hypocalcemia provoke rapid negative and positive changes in the serum PTH concentration respectively." (PMID 28018229, 2016).
Hypocalcemia (continued). "It was observed that the PTH-D1 levels overall were lower than the PTH-SC levels in both groups I and II, suggesting that perhaps postoperative PTH levels fell regardless of whether the patient would eventually develop clinically relevant hypocalcemia or not." (PMID 22399155, 2012). "CC in hypoparathyroidism are related to the duration of hypocalcaemia and hyperphosphatemia (abnormally low CPR), not to parathyroid hormone itself, as in patient 3 with a normal parathyroid hormone level." (PMID 41473459, 2025). "We report a patient with PHP type 1a, with no documented evidence of hypocalcemia, presenting with AHO phenotype and multihormone resistance to PTH, TSH, and GnRH." (PMID 37908988, 2023). "The two PHP1b cases (P7, P8) presented with recurrent seizures due to hypocalcemia; neither exhibited any symptoms of AHO, presenting with only PTH resistance." (PMID 35296306, 2022). "Unlike PHPT, which is independent of PTH secretion by the parathyroid tissue, in SHPT, compensatory PTH secretion occurs due to hypocalcaemia." (PMID 32746794, 2020). "With CKD stage 4, the number of nephrons is reduced to the point that the increases in PTH and FGF23 are not able to augment P excretion and hyperphosphatemia, together with hypocalcemia, develops." (PMID 32913635, 2020). "We have not established a correlation between preoperative PTH, ALP and calcium levels, and postoperative hypocalcemia." (PMID 27737322, 2016). "The sensitivity, specificity, and both positive and negative predictive values were comparable between the threshold PTH level of 10 pg/mL on postoperative day 1 (POD1) and 4 h after surgery, and combining these measurements did not enhance the accuracy of predicting hypocalcemia after TT." (PMID 40786097, 2025). "However, it seemed not to significantly affect PTH on POD 30, transient hypoparathyroidism, and transient hypocalcemia." (PMID 35813620, 2022). "Additionally, patients with at least one well vascularized PG had higher ioPTH 3 and PTH on POD 1, which significantly suggested the absence of postoperative hypocalcemia." (PMID 35813620, 2022). "In 2015, rhPTH(1‐84) (Natpara; parathyroid hormone for injection) received US Food and Drug Administration (FDA) approval as an adjunct to calcium and active vitamin D to control hypocalcemia in patients with HP who are not well controlled on conventional therapy." (PMID 32212275, 2020). "Finally, in advanced CKD, hyperphosphatemia and hypocalcemia is present because the marked reduction of glomerular filtration makes FGF23 and PTH non-operative." (PMID 30909513, 2019). "Recovery of p-Ca2+ from hypocalcemia resulted in lower levels in NX-TPTX than in TPTX rats, 1.20 ± 0.02 vs.1.30 ± 0.02 (p < 0.05) demonstrating that absence of kidneys significantly affected the rapid regulation of p-Ca2+ independent of PTH, C-PTH and CT." (PMID 25885328, 2015). "However, our high-calcium rescue diet experiments ruled out hypocalcemia and secondary hyperparathyroidism as primary drivers of BAT thermogenesis in VDD offspring, as normalizing calcium and PTH levels did not prevent the enhanced BAT recruitment at 4 °C or the improved cold tolerance." (PMID 40429675, 2025). "Nevertheless, an increased PTH concentration is usually not enough to normalize phosphate and calcium levels; therefore, the most common set of laboratory abnormalities in CKD includes hypocalcemia, hyperphosphatemia and significantly elevated PTH with vitamin D deficiency." (PMID 40077644, 2025).
osteoporosis (891 papers, 1997 to 2026). A condition of reduced bone mass, with decreased cortical thickness and a decrease in the number and size of the trabeculae of cancellous bone (but normal chemical composition), resulting in increased fracture incidence. "Senolytic co‐treatment reduces senescence and prevents bone loss after PTH withdrawal, enhancing the durability of osteoporosis therapy." (PMID 41432314, 2026). "Parathyroid hormone (PTH) is a widely used anabolic therapy for osteoporosis; however, rapid bone loss after treatment discontinuation presents a significant clinical challenge." (PMID 41432314, 2026). "Approximately 20–50% of NF-1 patients have osteoporosis, which is associated with alterations in bone transformation biochemical markers, including decreased serum 25-hydroxyvitamin D and elevated serum PTH levels." (PMID 41170329, 2025). "Research has demonstrated that heightened PTH concentrations promote bone mineral demineralisation and escalate the risk of osteoporosis." (PMID 40007853, 2025). "The treatment with recombinant PTH (teriparatide) or the sclerostin inhibitor (romosozumab) is reserved for patients with osteoporosis at very high risk for fracture." (PMID 41393738, 2025). "Parathyroid hormone (PTH) is an FDA-regulated anabolic agent to reduce the risk of bone fracture in osteoporosis patients." (PMID 40507663, 2025). "Laboratory parameters, including serum albumin, calcium, phosphate, uric acid, parathyroid hormone (PTH) level, bone turnover markers and lipid profile were explored for potential associations with osteoporosis and fractures." (PMID 40721250, 2025). "Elevated HRs were observed across age (50–60 vs. 60–100 years), sex, HbA1c, BMI, PTH, and calcitonin levels, indicating consistent increased risk of osteoporosis, low T-score, and fractures in the COVID-19 cohort." (PMID 40870365, 2025). "This is consistent with the clinical subcutaneous daily administration of PTH to treat osteoporosis patients and reduce fracture risk." (PMID 40507663, 2025). "In this study, we demonstrate that a PTH threshold of 40 pg/mL is a significant risk factor for the development of VitD deficiency and the onset of osteoporosis." (PMID 41301518, 2025). "Patients with preoperatively high serum calcium, PTH, alkaline phosphatase, and skeletal manifestations such as osteitis fibrosa cystica, brown tumors, and severe osteoporosis are at higher risk of developing HBS." (PMID 41163950, 2025). "Elevated PTH levels suggest primary or secondary hyperparathyroidism, a common cause of bone turnover and osteoporosis." (PMID 40979723, 2025). "In this study, we demonstrate for the first time that a PTH threshold of 40 pg/mL represents a clinically significant risk factor for both 25(OH)D deficiency and the early onset of osteoporosis." (PMID 41301518, 2025). "Clinically, PTH has been effectively utilized to address bone loss conditions, such as osteoporosis, primarily due to its anabolic effects on bone mineral density." (PMID 40136530, 2025). "Over time, the presence of high PTH levels can lead to reduced bone mineral density, as bone formation is unable to equal the rates of resorption, increasing the risk of osteoporosis and fractures." (PMID 38674789, 2024). "RUNX2 is associated with PTH and osteoporosis and plays a crucial role in osteoblast differentiation." (PMID 39086902, 2024). "Teriparatide, a recombinant human parathyroid hormone, is an anabolic treatment for osteoporosis with a high risk of fractures." (PMID 38496066, 2024). "Otherwise, the bone stores about 60% of the overall amount of magnesium, and its deficiency contributes to osteoporosis directly by acting on crystal formation and indirectly by affecting PTH." (PMID 38247490, 2024). "High PTH levels can lead to CKD-associated osteoporosis via increased cortical porosity and thinning due to endocortical trabecularization." (PMID 39697967, 2024).
osteoporosis (continued). "The study concluded that in a diverse real-world setting, romosozumab prescribed for osteoporosis is associated with less adverse CV events compared with PTH analog therapy." (PMID 38987505, 2024). "Sold under the brand name Forteo (Eli Lilly and Company, Indianapolis, IN) teriparatide is a synthetic analog of human parathyroid hormone (PTH) intended for the treatment of osteoporosis in individuals at high risk of fractures." (PMID 39006724, 2024). "Elevated PTH levels can stimulate bone resorption, leading to bone loss and decreased bone mineral density, which can increase bone turnover and osteoporosis risk." (PMID 38172731, 2024). "PTH acts on osteoclasts, causing severe bone pain, osteoporosis, bone collapse, deformity, periarticular lesions, and pathological fractures." (PMID 39027473, 2024). "We found a significant association of a lower BMI, osteoporosis and lower parathyroid hormone levels with the risk of further fragility fractures." (PMID 39513358, 2024). "Surgical resection of the adenoma led to the normalization of serum calcium and parathyroid hormone levels, thereby reducing the risk of long term complications such as osteoporosis." (PMID 39109312, 2024). "Increased parathyroid hormone levels result in calcium resorption from bone, which weakens bones, causes skeletal losses, and accelerates the onset of osteoporosis." (PMID 38233891, 2024). "A metabolic disorder in the bone was the predominant feature, and renal wasting of phosphorus and calcium was linked to osteoporosis and increased intact parathyroid hormone (PTH) levels." (PMID 39176318, 2024). "Serum levels of PTH were found to increase with age in humans and are linked to age-related syndromes such as frailty, osteoporosis, and sarcopenia." (PMID 37742294, 2023). "A prior study showed that persistently high PTH levels led to an increased risk of osteoporosis and fractures." (PMID 37711876, 2023). "The second mechanism explained for the association between PPIs and osteoporosis is hypergastrinemia secondary to gastric acid suppression by PPIs, which can induce parathyroid hyperplasia and increase the PTH level." (PMID 37711876, 2023). "Changes in the ultradian PTH secretion pattern have been associated with various diseases including primary and secondary osteoporosis, and hyperparathyroidism." (PMID 36996072, 2023). "In the general population, low blood Mg level is associated with the development of type 2 diabetes and osteoporosis with an increase in PTH." (PMID 36769401, 2023). "This older age group showed significantly lower Z-scores and more risk factors, including a positive family history of osteoporosis, smoking, less physical activity, and higher parathyroid hormone levels when compared to the younger age group." (PMID 37836564, 2023). "Elevated PTH levels have been associated with sarcopenia, osteoporosis, and other age-related diseases." (PMID 36381723, 2022). "Magnesium deficiency directly causes osteoporosis by affecting the crystal formation, as well as the secretion and activity of the parathyroid hormone, and promotes the low grade inflammation that, consequently, increases osteoclasts activity." (PMID 35883807, 2022). "As a clinically approved drug for promoting bone anabolism, the role of PTH in osteoporosis caused by weightlessness is controversial." (PMID 36818465, 2022). "Magnesium deficiency also contributes to osteoporosis directly by acting on bone cells and altering crystal formation, and indirectly by affecting parathyroid hormone secretion and activity and promoting low-grade inflammation." (PMID 36143059, 2022). "Pharmacological inhibition of miR‐19a/b increases bone mass under physiological conditions, enhances the gain in bone mass by PTH therapy, and reverts bone loss in gonadectomy‐induced mouse models of osteoporosis." (PMID 36193848, 2022). "Forming a complex with SMAD4, it translocates into the nucleus to activate RUNX2, which is associated with PTH and osteoporosis." (PMID 36011354, 2022).